MTOR (mechanistic target of rapamycin kinase)
Diseases named in the same sentence as MTOR in open-access papers (continued):
Sharing a sentence is not in itself a finding about the gene and the disease.
Cognitive impairment (163 papers, 2010 to 2026). Abnormal cognition is characterized by deficits in thinking, reasoning, or remembering. "Further, our findings also elucidated a significant contribution of autophagy inhibition caused by activating the AKT/mTOR pathway in sevoflurane‐exacerbating cognitive impairment associated with tau pathology." (PMID 41405543, 2025). "Selective activation of mTOR in transgenic mouse models has been linked to improvements in cognitive deficits." (PMID 40450326, 2025). "mTOR regulates protein synthesis and long-term neuronal plasticity, and its dysregulation has been associated with cognitive impairments in AD." (PMID 39725872, 2024). "TSC1 and TSC2 proteins form a complex that inhibits mTOR activity; therefore, deletion of these proteins causes hyperactive mTOR signaling, intellectual impairment, refractory epilepsy, intellectual impairment, and an autistic-like phenotype." (PMID 39845785, 2024). "Recent studies showed that SGLT-2 inhibitors can affect the mTOR pathway and, as a result, function in reducing cognitive impairment linked to AD." (PMID 38002034, 2023). "Demethylation of H4K20me1 by Phf8 results in transcriptional suppression of RSK1 and homeostasis of mTOR signaling and causes cognitive impairments." (PMID 37143582, 2023). "Overall, DPG-triggered stimulation of autophagy and associated AMPK/mTOR pathway in the hippocampus contributes, at least in part, to the amelioration of cadmium-evoked cognitive impairment in rats." (PMID 38002000, 2023). "Rheb-mTOR is the key signaling pathway component that regulates cognitive impairment caused by autophagy dysfunction in the hippocampus during brain aging." (PMID 35634460, 2022). "Accordingly, we found a significant reduction in phosphorylated forms of Akt and mTOR, which are also seen in other models of toxin-induced neurodegeneration and are associated with cognitive impairment." (PMID 35656538, 2022). "Regarding the effect of mTOR pathway on CNS function, it is documented that hyperactivation of mTOR is associated with brain dysfunction and cognitive deficit." (PMID 35860429, 2022). "Other studies contested the protective effect of mTOR modulation in AD; activation of mTOR improves cognitive deficits and was associated with a reduction in Aβ-associated events." (PMID 34829854, 2021). "SGLT2 inhibitors are able to mimic those states by promoting catabolism and restoring mTOR cycling, thus decreasing cognitive impairment associated with metabolic diseases." (PMID 34885795, 2021). "The serotonin 5-HT6 receptor is a potentially relevant target in view of its ability to associate with neurofibromin and to engage the mTOR pathway to compromise cognition in several cognitive impairment paradigms." (PMID 34576341, 2021). "Collectively, these results demonstrate that the chronic intake of THC during adolescence induces a 5‐HT6 receptor‐dependent long‐lasting activation of mTOR signaling in the PFC that causes cognitive deficits in adulthood." (PMID 32329240, 2020). "The epigenetic disruption of RSK-mTOR-S6K signaling is involved in cognitive defects by loss of Phf8 and that the FDA-approved mTOR inhibitor rapamycin can rescue the behavioral and LTP deficits caused by Phf8 deletion." (PMID 29317619, 2018). "Two probes are found in a CpG island in the body of TSC2, which has been shown to be required for mTOR signaling in the brain, which has been associated with cognitive impairment." (PMID 24373378, 2013). "Considering the crucial role of autophagy in AD, we speculated that targeting AKT/mTOR‐mediated autophagy signaling may offer novel therapeutic avenues for sevoflurane‐induced cognitive impairment associated with tau pathology." (PMID 41405543, 2025). "Activation of autophagy via the AMPK/mTOR pathway could alleviate the cognitive impairment caused by conventional protein kinase C (cPKC)γ deficiency in T1DM mice." (PMID 38164477, 2024).
Cognitive impairment (continued). "However, mTOR and autophagy blockades are required for brain interneuron progenitor development, and the dysfunction or loss of mTOR signaling can lead to cognitive impairment." (PMID 37508898, 2023). "Collectively, these findings suggest that blocking the 5-HT6 receptor-mTOR pathway might be a promising strategy to alleviate cognitive deficits associated with neuropsychiatric disorders of different etiologies." (PMID 34576341, 2021). "Our data suggests that down regulation of mTOR signaling, leading to enhanced autophagy and lysosomal clearance of Aβ fibrils, underlies the beneficial effects of geniposide against neuropathological damage and cognitive deficits characteristic of AD." (PMID 30684442, 2019). "However, whether the AKT/mTOR‐mediated autophagy associated with sevoflurane exposure is involved in the regulation of AD‐related cognitive impairment remains unclear." (PMID 41405543, 2025). "Dysfunction or loss of mTOR signaling may at times result in cognitive impairment." (PMID 37508898, 2023). "Kelleher and Bear hypothesised that an increase in the activity of the mTOR pathway could lead to excessive plasticity-related synaptic protein synthesis that may result in changes in synaptic connectivity and cognitive impairment and be one of several pathogenic mechanisms leading to autism." (PMID 34576223, 2021). "However, mTOR activation is postulated to contribute to posttraumatic maladaptive hippocampal plasticity and cognitive impairment associated with posttraumatic epilepsy, a premise supported by improved outcomes associated with administration of the mTOR inhibitor rapamycin." (PMID 34095131, 2021). "Attenuation of mTOR negates these age‐associated changes in rats, suggesting that mTOR activity underlies the etiology of age‐associated microvascular and neuronal dysfunction and may thus drive cognitive impairment in normative aging." (PMID 31693798, 2020). "Strikingly, pharmacological TDO2 blockade, neuronal TDO2 knockdown or mTOR activation reverses synaptic and cognitive deficits in Sirt6 cKO mice." (PMID 42277466, 2026). "•PI3K/AKT/mTOR pathway inhibitor reduces the amelioration of cognitive deficits in Sev-anesthetized rats by high-dose GpS." (PMID 39708584, 2025). "In conclusion, MSC - Exos alleviate cognitive deficits after mTBI by inhibiting ferroptosis via PI3K/AKT/mTOR - mediated upregulation of GPX4, providing a novel therapeutic strategy for mTBI." (PMID 41261172, 2025). "Similar findings have been reported in APP/PS1 mice, where autophagic activation in neurons and microglia alleviated amyloid pathology and cognitive impairment through the AMPK/mTOR/ULK1 pathway." (PMID 40589337, 2025). "Since Aβ and p-tau, key AD hallmarks, are influenced by IR and insulin signaling components (P-AKT and p-mTOR), this explains the strong link between IR and AD, as well as the cognitive impairment observed in stressed rats during behavioral assessment." (PMID 40397120, 2025). "Restoring the circadian rhythms of mTOR enhancement can help with cognitive impairment and metabolic disorders." (PMID 40325262, 2025). "Our results are significant as they show that dietary salt leads to tau hyperphosphorylation, damages GLP-1R and activates mTOR/p70S6K pathway, which eventually leads to cognitive impairment in C57BL/6 mice." (PMID 38575652, 2024). "In this study, we investigated the effects of chronic parental HHcy on offspring to correlate brain structure changes and mTOR/autophagy dysregulation with the observed locomotor and cognitive impairments." (PMID 38559811, 2024). "Rapamycin administration can attenuate cognitive deficits in AD models through an increase in autophagy and/or decrease in hyperexcitability, further linking overactivation of mTOR activity and its contribution to AD." (PMID 38390593, 2024). "Liraglutide enhanced autophagy by activating AMPK/mTOR pathway and reduced cognitive impairment in STZ-induced diabetic mice." (PMID 38164477, 2024).
Cognitive impairment (continued). "The mTOR hyper-activation-induced impairment of γ-oscillations is likely to contribute to the cognitive impairment observed in early-stage AD and MCI since γ activity serves as an elementary operator of brain function and communication, as reviewed by Basar." (PMID 37163441, 2023). "Excessive activation of inflammatory pathways such as TLR4/NF-κB/NLRP3 and TLR4/Akt/mTOR promotes an increase in the central nervous system inflammatory response and participates in the occurrence and development of cognitive impairment." (PMID 37576498, 2023). "This highlights the potential importance of mTOR regulation in addressing cognitive impairment in AD." (PMID 38002034, 2023). "Precedent studies have demonstrated that the deregulation of mTOR signaling participates in cognitive impairment by modulating autophagy." (PMID 37686031, 2023). "Collectively, the present study offers compelling evidence that the aberrant m6A demethylase FTO contributes to synaptic and cognitive impairment in neonatal HIBD by activating Akt/mTOR-mediated autophagy through the destabilization of PTEN mRNA." (PMID 38092760, 2023). "In the brain, TMAO induces neuronal aging, increases oxidative stress, damage’s mitochondrial function, inhibits rapamycin target protein (mTOR) signaling, and can lead to brain aging and cognitive impairment." (PMID 37191418, 2023). "This modulation of the mTOR pathway aligns with the proposed benefits of restoring circadian mTOR rhythm to counteract cognitive impairment." (PMID 38002034, 2023). "In studies related to hypoxia-induced cognitive impairment, special mention has been made of the mTOR signaling pathway, the alterations in vivo have been associated with various neurological disorders." (PMID 36860517, 2023). "The advantage of our study is that it overcomes the limitations of the extensive previous PI3K/AKT/mTOR-based studies on cognitive disorders." (PMID 37517091, 2023). "Rapamycin attenuated mTOR/p70S6k, increased Nrf2/HO-1 activity, and attenuated tau pathology, oxidative stress, and cognitive deficits induced by zinc in a rat model." (PMID 35197970, 2022). "Anesthesia/surgery led to mammalian target of rapamycin (mTOR) hyperactivity in the hippocampus and interfered with synaptic proteins homeostasis by inhibiting autophagy and resulted in cognitive impairment." (PMID 35370607, 2022). "In conclusion, our findings imply that rapamycin prevents zinc-induced cognitive impairment and protects neurons from tau pathology, oxidative stress, and synaptic impairment by decreasing mTOR/p70S6K hyperactivity and increasing Nrf2/HO-1 activity." (PMID 35197970, 2022). "Evidence has identified that dysregulation of mTOR signaling is involved in cognitive impairment by modulating autophagy." (PMID 34784444, 2022). "It is believed that restoring the circadian rhythm of mTOR activation would be beneficial in metabolic diseases and cognitive impairment." (PMID 34885795, 2021). "This study will elucidate if pharmacological mTOR inhibition during critical neurodevelopmental time windows alleviates cognitive impairments in mTORopathies." (PMID 34828352, 2021). "An mTOR inhibitor, rapamycin, ameliorated anesthesia/surgery-related cognitive impairments by inhibiting the mTOR activity, inducing activation of autophagy, enhancing SYN and PSD-95 expression." (PMID 33935683, 2021). "Together with the present results, these findings suggest that both enhanced Erk and mTOR activities contribute to cognitive impairment in NF1 and that deregulation of each pathway affects distinct cognitive functions." (PMID 34576341, 2021). "Several groups report dramatic up-regulation of basal (unstimulated) mTOR signaling markers in AD, mild cognitive impairment (MCI) and preclinical AD patients." (PMID 34215308, 2021). "mTOR (mechanistic/mammalian target of rapamycin) is a novel, promising molecular pathway linking metabolic diseases and cognitive impairment." (PMID 34885795, 2021).
Cognitive impairment (continued). "In connection with cognitive impairment, rapamycin, an mTOR inhibitor, can reverse the increase of mTOR activity in PFC like a 5-HT6 antagonist, thus improving cognitive disorder induced by 5-HT6 agonists." (PMID 33628219, 2021). "Several studies emphasize the close link between cognitive impairment in AD and mTOR signaling and the presence of amyloid β plaques." (PMID 32655767, 2020). "mTOR dysregulation contributes to age‐dependent tissue dysfunctions, including cognitive impairment." (PMID 31762159, 2020). "Inhibition of GSK3 β restored the acidification of autophagy lysosome via inhibiting mTOR, promoted the autophagy clearance of pathological β-amyloid protein, and alleviated cognitive impairment in AD mice." (PMID 32382276, 2020). "For instance, hyperactivation of the PI3K/Akt/mTOR pathway has been reported in post-mortem tissue from the inferior parietal lobe of amnestic mild cognitive impairment and AD patients compared to controls." (PMID 32719587, 2020). "Rapamycin, an mTOR inhibitor, decreased amyloid deposits and tau tangles, and reduced cognitive deficits in 3xTg and PDAPP mice." (PMID 33322202, 2020). "Given the involvement of mTOR -autophagy pathway in the clearance of Aβ, we evaluated the molecular mechanism of chronic psychological stress affected cognitive impairments." (PMID 32372981, 2020). "The sustained increase mTOR signaling in PFC of THC‐treated mice plays a key role in the emergence of cognitive deficits in adulthood." (PMID 32329240, 2020). "mTOR inhibitor rapamycin activates autophagy, alleviates the accumulation of Aβ and ameliorates cognitive deficits in mice expressing mutant APP." (PMID 32457595, 2020). "In AD, there is ample evidence suggesting that hyperactive mTOR contributes to the accumulation of Aβ and cognitive impairment." (PMID 31607908, 2019). "In the present study, rapamycin caused a marked improvement despite memory impairment induced by isoflurane exposure, which suggested that mTOR signaling was involved in postoperative cognitive deficits." (PMID 31803045, 2019). "This is further supported by studies that show that treatment with mTOR inhibitors improves the cognitive impairment in AD." (PMID 31680874, 2019). "The mammalian target of rapamycin (mTOR) signaling system plays a key role in both normal brain development and in a wide range of developmental disorders that are characterized by cognitive deficits." (PMID 30083288, 2018). "In humans, phosphorylation of PI3K p85α subunit at the Tyr508 residue and Akt at the Ser473 residue were detected during the early stages of mild cognitive impairments, indicating involvement of mTOR in the development of AD." (PMID 31194026, 2018). "In the brain, TMAO has been shown to induce neuronal senescence, increase oxidative stress, impair mitochondrial function, and inhibit mTOR signaling, all of which contribute to brain aging and cognitive impairment." (PMID 30579367, 2018). "Evidence has confirmed that ginsenoside Rg1 improved age‐related cognitive deficit by up‐regulating the expression levels of the mTOR signalling pathway (Yang, Zhang, Zheng, Shen & Chen, 2014)." (PMID 29749694, 2018). "Linking this signalling event to cognitive impairment, the mTOR inhibitor rapamycin prevented deficits in social cognition and novel object discrimination induced by 5-HT6 agonists." (PMID 23027611, 2012). "Indeed, in animal models, pharmacological inhibition of mTOR with rapamycin has been shown to rescue behavioral deficits, including depressive-like behavior and cognitive deficits." (PMID 41578026, 2026). "Improved cognitive deficits; reduced white matter injury; modulated mTOR-mediated autophagy." (PMID 41230091, 2025). "Furthermore, autophagy can be regulated by mammalian target of rapamycin (mTOR), as reducing its hyperactivity in AD mice reverses cognitive deficits and repairs CNS autophagy." (PMID 40420360, 2025).
Cognitive impairment (continued). "In AD, a body of increasing evidence indicates that the inhibition of the AKT/mTOR signaling pathway may contribute to alleviating AD‐related cognitive impairment and pathological manifestations." (PMID 41405543, 2025). "In summary, we found that P301S‐tau downregulated TECPR1 protein levels, leading to autophagy dysfunction by activating the mTOR signaling pathway, and exacerbating tau accumulation, ultimately resulting in synaptic plasticity impairments and cognitive deficits." (PMID 39511758, 2025). "Furthermore, we investigated the contribution of the BDNF/TrkB/mTOR signalling pathway to Rep lido‐induced cognitive impairment in aged mice." (PMID 41318982, 2025). "Additionally, multiple studies have reported that anesthesia and surgery activate the mechanistic target of rapamycin (mTOR) pathway, which negatively regulates cellular autophagy and contributes to post-operative cognitive impairment." (PMID 40914484, 2025). "However, it has been recently shown that aberrant protein aggregation, such as deposition of beta-amyloid (Aß) and tau filaments, as well as cognitive impairment, are chased away by the inhibition of mTOR." (PMID 41155356, 2025). "However, we used GLP-1R agonists in vitro in this study, so further in vivo experiments are needed to confirm that the silence of GLP-1R can inhibit autophagy and lead to cognitive impairment by activating mTOR/p70S6K pathway." (PMID 38575652, 2024). "Research on animal models shows that inhibition of mTOR pathway and its downstream signals by rapamycin may improve cognitive impairment by preventing neural apoptosis." (PMID 37721413, 2024). "Injection of IGF2, a molecule that induces mTOR signaling, could fully rescue cognitive impairment and IEG expression in aging Tsc2+/− animals." (PMID 39192595, 2024). "Seizures have been shown to both activate mTOR and worsen AD pathology and cognitive deficits." (PMID 38390593, 2024). "Chronic corticosteroid administration is associated with reductions in hippocampal volume, increased neuronal apoptosis, and dysregulation of the mammalian target of rapamycin (mTOR) signaling pathway, all of which contribute to the cognitive impairments observed in affected patients." (PMID 39335644, 2024). "Similarly, the CRS-treated ICR mice were subjected to cognitive deficits with the decreased AKT/mTOR in hipppocampus." (PMID 36969556, 2023). "It is important to note though that the activity of mTOR may be required to some degree, since studies suggest that dysfunction in mTOR signaling can result in cognitive impairment and synaptic dysfunction." (PMID 37238686, 2023). "Rapamycin, an inhibitor of mTOR, rescued zinc-induced increases in mTOR/p70S6K activation, tau phosphorylation, and oxidative stress, and Nrf2/HO-1 inactivation, cognitive impairment, and synaptic impairment reduced the expression of synapse-related proteins in zinc-injected rats." (PMID 35197970, 2022). "Streptozotocin induced diabetic mice also develop activation of mTOR and cognitive impairment." (PMID 35276811, 2022). "Melatonin could inhibit neuroinflammation by suppressing mTOR signaling in the hippocampus of aged mice, thereby reducing isoflurane-induced cognitive impairment." (PMID 35356294, 2022). "In addition, chlorogenic acid treatment can protect Aβ-induced injury in SH-SY5Y neurons and alleviate cognitive impairments in AD transgenic mice via enhancing the activation of the mTOR/TFEB signaling pathway." (PMID 35214904, 2022). "Moreover, increasing p62 expression in an APP/PS1 mouse model resulted in autophagy activation by a mTOR-independent pathway, leading to a reduction of Aβ pathology and amelioration of cognitive deficits." (PMID 34829854, 2021). "Moreover, genetic reduction or early pharmacological suppression of mTOR has been shown to rescue cognitive deficits, reduce Aβ deposition and intracellular tau accumulation along with an increase of autophagy induction in AD mice." (PMID 34315531, 2021).